CXCL8 (C-X-C motif chemokine ligand 8)
Diseases named in the same sentence as CXCL8 in open-access papers (continued):
Sharing a sentence is not in itself a finding about the gene and the disease.
rheumatoid arthritis (195 papers, 2006 to 2025). A chronic, systemic autoimmune disorder characterized by inflammation in the synovial membranes and articular surfaces. "Accordingly, CXCL8 has been implicated in a number of inflammatory diseases, including inflammatory bowel disease and rheumatoid arthritis." (PMID 24276377, 2013). "Production of IL-8, sometimes called chemokine (C-X-C motif) ligand 8 or CXCL-8, is a hallmark of inflammation and responsible for neutrophil recruitment and activation and in several age-related diseases such as osteoporosis, Alzheimer’s disease (AD), or rheumatoid arthritis." (PMID 35935995, 2022). "The DEGs which contributed to the pathway term “Rheumatoid arthritis” were CXCL8 (C-X-C Motif Chemokine Ligand 8), CTSL (Cathepsin L), CXCL2 (C-X-C Motif Chemokine Ligand 2), and CCL2 (C-C Motif Chemokine Ligand 2)." (PMID 36911677, 2023). "This study aimed to further investigate the correlation between three effective biomarkers (JUN, SOCS3, CXCL8) and immune infiltrating cells, which play a crucial role in rheumatoid arthritis (RA), specifically in RF-negative pJIA and oJIA." (PMID 38001449, 2023). "The Enrichr pathway assignment analysis (KEGG 2021 Human database) additionally revealed enrichment of chemokine encoding genes (CXCL1, CXCL2, CXCL3, CXCL6, CXCL5, CXCL8, CCL2) which were aligned to several pathways like amoebiasis and rheumatoid arthritis." (PMID 35646693, 2022). "(2018) observed that supervised exercise was effective in promoting neutrophil migration through CXCL8/IL-8 (p=0.003) in patients with rheumatoid arthritis." (PMID 36685603, 2022). "TNF-alpha, IL-1beta, CXCL8, and CXCL10 levels have been linked with ankylosing spondylitis and crystal, psoriatic and rheumatoid arthritis." (PMID 35153741, 2021). "In the rheumatoid arthritis pathway, a total of 5 DEGs were enriched, among which IL-8/CXCL-8 is a key mediator related to inflammation belonging to the CXC family of chemokines that is usually released in response to inflammatory stimulation." (PMID 31673142, 2019). "In rheumatoid arthritis, a chronic inflammatory disease affecting the diarthrodial joints, CXCL8 mediates neutrophil recruitment and BET protein inhibition reduces collagen induced arthritis in mice." (PMID 25713319, 2015). "Since TNF-α and IL-1β are implicated in arthritis, synovial concentrations of CXCL8 and CXCL10 were compared in patients suffering from crystal arthritis, ankylosing spondylitis, psoriatic arthritis and rheumatoid arthritis." (PMID 16846531, 2006). "CXCL8 is known to be elevated in PBMCs of patients with active rheumatoid arthritis." (PMID 36911677, 2023). "Furthermore, CXCL8 is induced to a greater extent in synovial fibroblasts from patients with PsA than in rheumatoid arthritis." (PMID 37131254, 2023). "CXCL8 is a broad-spectrum inflammatory marker that is elevated in rheumatoid arthritis (RA), reflecting the degree of neutrophil-mediated inflammation." (PMID 40606658, 2025). "Interestingly, neuropeptides demonstrated to foster CXCL8 production by fibroblast-like synoviocytes and may as such contribute to neutrophilic inflammation and joint damage in rheumatoid arthritis (RA)." (PMID 36725964, 2023). "Extending these studies to primary cells, these lead compounds also reduced IL-6 and CXCL8 production by TNF stimulated fibroblast-like synoviocytes (FLS) from rheumatoid arthritis (RA) patients." (PMID 33390996, 2020). "More recent evidence has demonstrated increased levels of CXCL8, CXCL9, CXCL10, and CCL20 in rheumatoid arthritis, indicating the importance of chemokines in inflammatory bone diseases." (PMID 33510341, 2021). "For example, CXCL8, CXCL2, or GRO1 were involved in rheumatoid arthritis, legionellosis, salmonella infection, and so on." (PMID 31921295, 2019). "CXCL8/IL-8 has been shown to promote NET formation, impair wound healing in type 2 diabetes, and contribute to enhanced neutrophil infiltration and NET production in the synovium of rheumatoid arthritis." (PMID 40963602, 2025).
rheumatoid arthritis (continued). "In patients with rheumatoid arthritis, a negative correlation of the levels of IL-1RA, IL-6, and CXCL8 with the expression of the CYP3A4 phenotype of the CYP family was detected." (PMID 35408801, 2022). "Gastrodia elata Blume (GE) is a traditional Chinese herbal medicine with anti-inflammatory activity, and according to a study, GE significantly decreased the IL-6, CXCL8, MMP-3 and MMP-13 levels in TNF-induced rheumatoid arthritis fibroblast-like synoviocytes (RA-FLSs)." (PMID 36439173, 2022). "Moreover, this study is the first to report site-specific cleavage of CXCL8 in synovial fluids from patients with rheumatoid arthritis (RA) and juvenile idiopathic arthritis (JIA), thereby opening a window of oppurtunitiy for identification of disease biomarkers and potential therapeutic targets." (PMID 33777041, 2021). "Serum levels of the inflammatory factors CXCL8 and CCL20 are elevated in rheumatoid arthritis, but whether these factors affect bone metabolism is unknown." (PMID 26103626, 2015). "In contrast, compared with crystal arthritis, only rheumatoid arthritis patients, and not ankylosing spondylitis or psoriatic arthritis patients, had significantly higher synovial CXCL8 concentrations." (PMID 16846531, 2006). "However, CXCL8 and CCL20 enhanced osteoblast-mediated osteoclastogenesis, partly via IL-6 production, suggesting that CXCL8 and CCL20 may contribute to osteoporosis in rheumatoid arthritis by affecting bone cell communication." (PMID 26103626, 2015). "TNFα, IL-1β, and hypoxia also up-regulate the expression of cytokines, including IL-6, CXCL8 (namely, IL-8), CCL2, CXCL11, CXCL12, and VEGF, as well as the expression of cytokine receptors such as TNFRSF9 in synovial fibroblasts derived from rheumatoid arthritis (RA) patients." (PMID 35967331, 2022).
colitis (152 papers, 2009 to 2026). Inflammation of the colon. "As expected, the conditioned media demonstrate that colitis-associated (N = 11) and cancer-associated fibroblasts (N = 5) exhibit increased levels of CXCL8 compared to that of normal colon fibroblasts (N = 6)." (PMID 29560130, 2018). "The data so far demonstrated that changes in miR-20a levels are inversely related to the levels of the chemokine, CXCL8, which may influence the tumor promoting activity of colitis-associated fibroblasts." (PMID 29560130, 2018). "Moreover, miR-20a and CXCL8 show an inverse relationship that models the transitions of the interstitial fibroblasts from normal to colitis-to tumor associated." (PMID 29560130, 2018). "Epimedin A1 significantly elevates RvD5 levels in colonic tissue, suppresses CXCL8 expression in colonic epithelial cells, and reduces mucosal epithelial neutrophil infiltration in colitis mice." (PMID 41631883, 2026). "Accordingly, there was a significant correlation between CH25H and CYP7B1 expression and colonic inflammation (as measured by CXCL8 expression) in humans with ulcerative colitis." (PMID 29343433, 2018). "As expected from our previous work, the levels of CXCL8 varied depending on disease state and statistically significant changes were seen between colitis and cancer compared to normal colon." (PMID 29560130, 2018). "However, the specific mechanisms through which CXCL8 drives NET formation in colitis remain unresolved and warrant further investigation." (PMID 40963602, 2025). "Moreover, the intestinal cells have up-regulation of pro-inflammatory chemokines like C-X-C motif chemokine ligand (CXCL) 1 (CXCL1), CXCL3, and CXCL8, which only perpetuates the inflammatory cycle of colitis." (PMID 36677021, 2023). "We conclude that in addition to its known microbicidal action, cathelicidin has a unique pathogen-sensing role, facilitating LPS-mediated intestinal responses, including the production of CXCL8/CXCL1 that would contribute to an integrated tissue response to recruit neutrophils during colitis." (PMID 32658599, 2020). "We found that there were 15 analytes upregulated in both DSS and C. rodentium colitis, including innate immune cell-associated cytokines (G-CSF, IL-1β, TNF-α, LIF, and IL-6), chemokines (CCL2, CCL5, CCL11, CXCL2, CXCL8, CXCL9, MIP-1α, and MIP-1β), and Th1 (IFN-γ) and Th17 (IL-17) cytokines." (PMID 30972302, 2019). "Therefore, TRPM2-mediated Ca2+ influx is important in ROS-induced CXCL2/CXCL8 production by monocytes and neutrophil infiltration that, if heightened to colon inflammation, lead to colitis." (PMID 26300888, 2015). "Nonetheless, further studies are needed to elucidate the precise mechanisms by which CXCL8 and S100A8/A9 drive NET formation in colitis." (PMID 40963602, 2025). "The activation of LXRs in a mouse colitis model can suppress the expression of inflammatory factors such as IL-1β, IL-6, IL-17A, TNFα, and chemokines such as CXCL1/KC, CXCL2/MIP2, CXCL8/IL-8, CCL2/MCP1 and CXCL10 in the colon tissue." (PMID 37720208, 2023). "Upregulated mucosal expression of numerous chemokines and their counter receptors including CXCL8 (IL-8)/CXCR2, CXCL9,10,11/CXCR3, CCL25/CCR9, CCL19,21/CCR7, and CCL20/CCR6 is evident in active IBD and in models of colitis." (PMID 22162719, 2012). "In colitis and CAC, microenvironmental fibroblasts exhibit an activated, inflammatory phenotype that contributes to tumorigenesis accompanied by excessive secretion of the chemokine CXCL8." (PMID 29560130, 2018).
hepatocellular carcinoma (145 papers, 2004 to 2026). A malignant tumor that arises from hepatocytes. "High HIF-1α and CXCL8 are associated with the development of hepatocellular carcinoma and metastasis." (PMID 40076892, 2025). "Tumour-infiltrating monocytes also secret CXCL8, which is positively associated with human hepatocellular carcinoma." (PMID 35894174, 2022). "Especially the recent study from Huang and coworkers underlines the impact of CXCL8 on hepatocellular carcinoma metastasis formation in mice via increased FOXC1 expression." (PMID 26859141, 2016). "In hepatocellular carcinoma, CXCL8 upregulation was linked to more aggressive invasion." (PMID 37031328, 2023). "Monocytes-derived CXCL2 and CXCL8 are the main causes in regulating neutrophils' recruitment into TME of hepatocellular carcinoma, which could inhibit cancer cell apoptosis." (PMID 34474677, 2021). "Additionally, CXCL8, released by activated stellate cells, has been linked to hepatocellular carcinoma (HCC) angiogenesis." (PMID 38515019, 2024). "PFKFB3-NF-κB signaling induced the production of CXCL2 and CXCL8 in tumor-infiltrating monocytes, increased levels of CXCL2 and CXCL8 in monocytes and promote infiltration of oncostatin M-producing neutrophils in human hepatocellular carcinoma tissues." (PMID 37253634, 2023). "A study showed that the AP-1/PEA3 complex binds to IL-8/CXCL8 promoter in human hepatocellular carcinoma." (PMID 34229599, 2021). "In patients with hepatocellular carcinoma the presence of high expression of CXCR2 and its ligands CXCL5 and CXCL8 (IL-8) on tumor cells are associated with neutrophil recruitment and neoplastic cell spreading." (PMID 27618112, 2016). "An inflammatory microenvironment involving also CXCL8 seems to play an important role in hepatocellular carcinoma and its metastasis formation in general." (PMID 26859141, 2016). "We analyzed correlation between HIF-1α and CXCL8 levels, tumor characteristics and overall survival in 102 hepatocellular carcinoma (HCC) patients." (PMID 26078356, 2015). "Interestingly, the role of chemokines like CXCL8 in liver cirrhosis and their potential as biomarkers for early detection of hepatocellular carcinoma (HCC) highlight the intricate relationship between immune signaling and liver disease progression." (PMID 41223189, 2025). "In hepatocellular carcinoma and osteosarcoma, CXCL8 may enhance cancer-cell invasion via the PI3K/Akt signaling pathway." (PMID 36295640, 2022). "Indeed, human liver epithelial cells from hepatocellular carcinoma have been shown to produce the CXC chemokine CXCL8 and promote neutrophil infiltration." (PMID 25372289, 2014). "CXCL8 is associated with resistance to multiple chemotherapeutic approaches including platinum-based drugs in ovarian cancer, epidermal growth factor receptor (EGFR) inhibitors in lung cancer, cisplatin and doxorubicin in hepatocellular carcinoma, and gemcitabine in pancreatic cancer." (PMID 40076892, 2025). "A phase II clinical trial (NCT04050462) is ongoing with an anti-CXCL8 antibody (BMS-986253) in combination with nivolumab (anti-PD-1 antibody) in patients with advanced hepatocellular carcinoma (HCC)." (PMID 35158948, 2022). "The mutual binding of CXCL8 to CXCR2 activates downstream signaling pathways and enhances the invasiveness of various tumors, including hepatocellular carcinoma (HCC), making it a potential therapeutic target." (PMID 40006729, 2025). "In ongoing phase II clinical trials for treatment of NSCLC and hepatocellular cancer, BMS-813160 is being administered in combination with nivolumab and the anti-CXCL8 drug BMS-986253 (NCT04123379)." (PMID 37114134, 2023). "In hepatocellular carcinoma cells, PEA3 interacted with AP-1 to regulate IL-8/CXCL8 gene expression." (PMID 34229599, 2021). "Among the different systems the human hepatoma cell line HuH7 was most responsive with significant up-regulation of the genes coding for SOCS3, CXCL8 and mitogen activated protein kinases." (PMID 30547786, 2018).
hepatocellular carcinoma (continued). "Additionally, CXCL8 regulates hepatocellular carcinoma (HCC) cell proliferation and migration." (PMID 36072669, 2022). "Also, CXCL16 increases CXC motif chemokine ligand 8 (CXCL8)/IL-8 expression in prostate PC3 and C4-2B cancer cells and in hepatocellular carcinoma SK-HEP-1 and HCCLM3 cells." (PMID 33800554, 2021). "Moreover, the release of human CXCL8 (IL-8) was only attenuated in human hepatoma cells but not in endothelial or stellate cells by ADAM8 knockdown." (PMID 33814981, 2021).
glioblastoma (140 papers, 2010 to 2026). The most malignant astrocytic tumor (WHO grade IV). "Our data also indicate that CXCL8 is a significant prognostic biomarker associated with poor progression-free survival (PFS) in glioblastoma patients from the TCGA dataset and is a predictor of poor OS in the CGGA cohort." (PMID 41432874, 2025). "Up-regulation of CXCL8 in glioblastoma cells was also shown to be caused by Bcl-xL and is mediated through a nuclear factor-kappa B (NF-kB)-dependent mechanism." (PMID 35269652, 2022). "Notably, CXCL8 expression has been linked to higher plasma levels in glioblastoma patients, which correlates with shorter overall survival (OS)." (PMID 41432874, 2025). "This concept is consistent with emerging evidence highlighting CXCL8’s role in reprogramming the glioblastoma stem‐cell niche toward a mesenchymal, TAM-polarizing state." (PMID 41432874, 2025). "Specifically, CXCL8 expression was highly correlated with M2 macrophage infiltration in both primary and recurrent glioblastoma, further emphasizing its potential as a target for future therapeutic strategies." (PMID 41432874, 2025). "Previous studies have shown a correlation between CXCL8 expression and poor outcomes in various cancers, including glioblastoma." (PMID 41432874, 2025). "For instance, ALKBH5 stabilized lncRNA NEAT1 transcript via m6A demethylation and thus facilitated lncRNA NEAT1-mediated paraspeckle assembly, ultimately promoting glioblastoma multiforme progress through upregulating downstream CXCL8/IL8 pathway." (PMID 38145297, 2024). "Downregulation of ALKBH5 in glioblastoma cells results in a significant decrease in CXCL8/IL8 production, leading to diminished recruitment of hypoxia-induced TAMs and attenuated immunosuppression." (PMID 38398118, 2024). "Suppression of ALKBH5 in glioblastoma cells significantly decreased CXCL8/IL8 production, diminished hypoxia-induced TAM recruitment, and immunosuppression in intracranial transplanted tumors." (PMID 35625706, 2022). "Silencing ALKBH5 in glioblastoma multiforme (GBM) notably suppresses hypoxia-induced tumor-associated macrophage (TAM) recruitment and immunosuppression in allograft tumors by regulating CXCL8/IL-8 secretion." (PMID 36225914, 2022). "Nets are produced by tumor-infiltrating neutrophils involved in glioblastoma cell proliferation and invasion through stimulation of the nuclear factor kappa B (NF-κB) signaling pathway, which promoted CXCL8 secretion in glioblastomas." (PMID 35011369, 2021). "Necrotic cells induce CXCL8 expression through AP-1/NF-κB activation that promote cell migration and invasion in glioblastoma." (PMID 35011369, 2021). "All the data obtained support the concept that autocrine CXCL8 signalling plays a key role in the activation of an aggressive phenotype in primary glioblastoma cells and U-87MG cell line." (PMID 31986121, 2020). "Overexpression of Bcl-xl in human glioblastoma cells induced an increased expression of CXCL8, both at the protein and mRNA levels, and an enhanced CXCL8 promoter activity." (PMID 32456359, 2020). "Starting from these evidences, in this work we first examined the expression of CXCR1/CXCR2 and secreted CXCL8 in human glioblastoma U-87MG cell line and primary cell cultures from post-surgical specimens of glioblastoma patients." (PMID 31986121, 2020). "Involvement of CXCL8 in the development and progression of glioblastoma has been extensively studied and reviewed." (PMID 31986121, 2020). "Several in-vitro studies suggest that NT acts on glioblastoma stem cells (GSC) via an IL-8/CXCL8 mechanism." (PMID 32336282, 2020). "We previously identified a novel function of BCL-XL in promoting tumor angiogenesis through the nuclear factor kappa B (NF-kB)/interleukin 8 (CXCL8) axis in tumor cell lines with a different origin, including glioblastoma and melanoma." (PMID 29238043, 2017).